IGF1 (insulin like growth factor 1)
Diseases named in the same sentence as IGF1 in open-access papers (continued):
Sharing a sentence is not in itself a finding about the gene and the disease.
cancer (continued). "These miRNAs and especially miR-223 which are involved in PI3K/AKT, IGF1, and MEK/ERK/NF-κB signaling cascades could represent a molecular link between inflammation and cancer." (PMID 34484116, 2021). "Additionally, KCC4 and its stimulators, EGF and IGF-1, are colocalized in the metastatic cancer tissues, suggesting the cooperation between KCC4 and EGF or IGF-1 in tumor metastasis." (PMID 35008759, 2021). "The correlation between IGF-1, IGF-1R, and cancer immunity was explored." (PMID 34804946, 2021). "In addition, CR, as well as reduced levels of IGF-1, can decrease genomic instability via Ras- or phosphatidylinositol-3 kinase (PI3K)/Akt/Tor/S6K-dependent mechanisms, which contribute to reducing cancer incidence in agreement with what was shown in yeast." (PMID 34572814, 2021). "It is thought that lanreotide could reverse the effects of high blood insulin/IGF1 concentration though activating the somatostatin receptor and inhibiting the PI3K/Akt/mTORC1 pathway in cancer cells." (PMID 35008233, 2021). "Neutralizing antibodies against five arbitrarily selected pleiotropic proteins present in MAs (TGF-β1, HGF, EGF, IGF-1, GRO-1) were used to check whether inhibition of these agents translates to decreased adhesion of cancer cells to PMCs or PFBs." (PMID 33921783, 2021). "Secondly, though IGF-1 and IGF-1R share the same signaling pathway, whether they have different prognostic and immunologic values in different types of cancer needs further investigation." (PMID 34804946, 2021). "We detected significant molecular signals of transcriptional interference with gene expression induced in human cancer cells in response to multiple growth factors such as epidermal growth factor (EGF), insulin-like growth factor-1 (IGF-1), transforming growth factor alpha (TGFA), and many others." (PMID 35155195, 2021). "On the other hand, the impact of low IGF1 on cancer prevalence has not yet been explored in a systematic fashion." (PMID 34769292, 2021). "IGF-1 and IGF-1R displayed inconsistent gene expression levels among diverse cancer cell lines." (PMID 34804946, 2021). "The prognostic impact of IGF-1 and IGF-1R expression among different cancer types was reported." (PMID 34804946, 2021). "The combined analysis of RNA-seq and ChIP-seq for H2A.Z showed downstream gene regulation to mainly occur via the transcriptional misregulation in the cancer pathway, its target genes mainly including TCF3 CDK14, JUP, SPINT1, CDKN1A, and IGF1, each of which corresponded to different cell phenotypes." (PMID 34120148, 2021). "Moreover, the potentiation of IGF-1-dependent proliferation by IGFBP3 was documented in fibroblasts, as well as some cancer cells 39,40." (PMID 34512163, 2021). "The expressions of IGF-1 and IGF-1R were correlated with TMB and MSI in some cancer types." (PMID 34804946, 2021). "IGF-1 treatment induced the expression of NANOG and OCT4 and sphere formation in HepG2.2.15, Hep3B, and PLC5 cell lines, and inhibition of IGF-1R by shIGF-1R suppressed cancer stemness properties in these cell lines." (PMID 33669204, 2021). "As abundant stromal cells in the TME, cancer-associated fibroblasts (CAFs) protect cancer cells from radiation-induced death and increase cancer cell radioresistance via paracrine action by cytokines, such as CXCL1, CXCL12, IGF1/2, and PDGF, eventually leading to RT failure and cancer progression." (PMID 34877934, 2021). "IGF-1 signals some of the same pathways as insulin, including PI3K, ERK, AKT, and mTOR, which could increase cancer cell proliferation and impair apoptosis." (PMID 33477579, 2021). "Typically, high expression level of IGF-1 and IGF-1R was detected in most malignant tumors." (PMID 34804946, 2021). "Our observation revealed for the first time that miR-186-3p acts as a carcinoma inhibitor in CC, at least in part, through the negative regulation of IGF1." (PMID 34551673, 2021).
cancer (continued). "Apart from higher levels of IGF-1, several cancers also overexpress its receptor IGF-1R, which has a negative impact on their progression." (PMID 32824177, 2020). "Our comprehensive analyses demonstrate that life-long lack of exposure to IGF1 in LS activates apoptotic, autophagic, and cancer-protecting pathways at the organism level." (PMID 33182502, 2020). "Proto-oncogenes are those genes that are involved in cell growth and proliferation, with potential examples including the ATM, FGFR2, FN1, IGF1, MAP3K, MMP7, and RHOC genes, while the CASP8 and LSP1 genes have been reported to possess tumor-suppressive properties in certain types of cancer." (PMID 33112566, 2020). "In this study, adaption of triple-negative breast MDA-MB-231 cancer cells to the CAF-secreted factors CXCL12 and IGF1 coincided with an increase in Src activity, which was then shown to be an result of an accumulation of pre-existing cells with a hyperactive Src pathway." (PMID 33228022, 2020). "The insulin-like growth factor-1 (IGF-1) binding to the insulin-like growth factor receptor-type 1 (IGF-1R) activates different transduction events, promoting the growth and survival of multiple types of cancer cells." (PMID 32325700, 2020). "It is well documented that the MAPK signaling cascade bridges the crosstalk between ECM-mediated extracellular signaling through growth factors and their receptors such as IGF-1/IGF-1R, and subsequent intracellular response to allow cancer cell proliferation and migration." (PMID 32660466, 2020). "α-SMA+ CAFs at the primary site of triple-negative (TN) breast tumors abundantly produced CXCL12 and IGF-1, the molecules that can select for cancer cells with high Src activity." (PMID 33050237, 2020). "In addition, CAFs are activated by exposure to radiation, which induces the secretion of insulin-like growth factor-1 (IGF-1) from CAFs, resulting in making cancer cells resistant to such therapy." (PMID 32260363, 2020). "Most importantly, studies with cells, tissues and animals show that GH/IGF-1 stimulates growth of these same cancers, while cancer growth without GH/IGF-1 activity is absent." (PMID 33312162, 2020). "For each organ-specific cancer cohort, we first evaluated relative differences between cases and controls for three spiked-in recombinant proteins—SDF-1β, IGF1, and IGFBP7, each of which served as internal quality control and was spiked in at a ratio case/control respectively of 1:10, 1:1, and 10:1." (PMID 33267867, 2020). "IGF-1, EGF, and estradiol induce cancer cell adhesion via IGF1R and activation of ERK1/2." (PMID 32069926, 2020). "We conclude that IGF-1 signals couple the induction of mitochondrial biogenesis with basal levels of mitochondrial turnover through Nrf2 and BNIP3, thus maintaining mitochondrial homeostasis and facilitating cancer progression." (PMID 31936236, 2020). "Strikingly, they do not develop cancer (nor diabetes), while overabundance of GH/IGF-1 links to cancer incidence." (PMID 33312162, 2020). "TGF-β and IGF-1 are known to induce EMT and the invasion of cancer cells." (PMID 32325994, 2020). "Later on, the enhanced expression of the SASP factors CXCL12, HGF, MMPs and TGFβ in irradiated fibroblasts was reported to increase EMT and invasiveness of cancer cells, and enhanced expression of the SASP factors EGF, FGF-4, GM-CSF, IGF-1,2, IGFBP-2,4,6 induced chemoradioresistance in cancer cells." (PMID 32384619, 2020). "As for other nutrients, high animal-protein diets may accelerate insulin-like growth factor-1 (IGF-1) secretion, promoting cancer incidence and progression, and carbohydrate-rich diets could be associated with BC prognosis through different mechanisms." (PMID 33374289, 2020). "On the other hand, the gene expression of grade 3 carcinoma revealed that the PDGF, IGF-1, and TRAIL pathways might be the important molecular mechanism to modulate tumor growth." (PMID 32640634, 2020).
cancer (continued). "Dissection of the complex regulatory loops involving the IGF1 and TXNIP pathways could be of relevance to our understanding of physio-pathological processes as well as to our ability to personalize cancer protocols." (PMID 31208077, 2019). "On the other hand, potential correlations between low IGF1 values and cancer incidence have not been investigated in a systematic fashion." (PMID 31208077, 2019). "Cancer cells secrete various molecules like transforming growth factor-β (TGF-β), vascular endothelial growth factor (VEGF), basic fibroblast growth factor (bFGF), insulin-like growth factor-1 (IGF-1) and interleukin-6." (PMID 31710263, 2019). "Reciprocally, activated PSCs produce PDGF, insulin-like growth factor 1 (IGF1), connective tissue growth factor (CTGF), and other factors that may promote cancer cell proliferation, migration, and survival." (PMID 31068602, 2019). "Insulin-like growth factor-1 (IGF-1) was found to induce PGC1β and PRC along with mitobiogenesis and mitophagy in cancer cell lines; of possible clinical significance, cells with acquired resistance to an IGF-1R inhibitor showed reduced expression of both PGC1β and PRC." (PMID 29361779, 2018). "Additionally, metformin reduces plasma levels of insulin and insulin-like growth factor 1 (IGF-1), which further constricts glucose availability to glycolysis-dependent cancer cells." (PMID 29971237, 2018). "Thus the crosstalk between CAFs and BC cells increases the secretion of IGF-1 in CAFs and PAI-1 activity in cancer cells." (PMID 29535813, 2018). "To determine whether IGF-1 promotes cancer cell invasion via the RhoA/ROCK pathway, we examined the effect of recombinant IGF-1 on RhoA-GTP expression." (PMID 29535813, 2018). "Hormonal factors such as insulin-like growth factor 1 (IGF-1) and leptin have been shown to be decreased by metformin administration and may potentially be responsible for the reduction of the cancer growth-supporting potential of patient sera." (PMID 29444159, 2018). "We wondered whether IGF-1 and IGF-2 might also be expressed in the metastatic tumor microenvironment and thereby provide a survival/proliferative signal to disseminated cancer cells." (PMID 29367764, 2018). "Independently of IGF-1, the crosstalk between CAFs and BC cells also increased the expression of PAI-1 in MDA-MB-231 cells, while geodin-inhibition of PAI-1 reduced RhoA activity in cancer cells, cancer cell scattering and invasion." (PMID 29535813, 2018). "Interestingly, IGF-1 maintains secretion of CCL5 from stromal cells, in particular mesenchymal stem cells that are in physical contact with PDAC cancer cells in vitro, resulting in the recruitment of tumor-targeting immune cells." (PMID 29475434, 2018). "In our study, we found that IGF-1 stimulated the phosphorylation of GSK-3β in PC12 cells, indicating that the inhibition of GSK-3β plays a positive role in promoting the development of cancer, at least in IGF-1R-mediated cancer." (PMID 30213025, 2018). "Instead the crosstalk between MDA-MB-231 cells and CAFs leads to increased migration, which depends on the activation of RhoA/ROCK/MLC signaling in cancer cells via two distinct mechanisms, the secretion of IGF-1 by CAFs and the upregulation of PAI-1 in cancer cells." (PMID 29535813, 2018). "AAS can also influence cancer cell proliferation via genomic and non-genomic mechanisms, such as the so-called estrogen-dependence mediated by ER, aromatase expression and IGF-1 production, which can even amplify each other." (PMID 29721213, 2018).
cancer (continued). "This group of cancers also correlates with high protein quality (represented by the “protein index”) and the fact that cancers of white blood cells in children are accompanied by excessively high IGF1 levels is unlikely to be a mere coincidence." (PMID 29951370, 2018). "We found six genes, ADIPOQ, DKK1, IGF1, IGF1R, IGF2, and PLAUR were shared by all the four cancers." (PMID 28676692, 2017). "Regarding the other cancer types without methylation-driven mechanisms related to IGF1, the expression level of IGF1 was identified as -0.87." (PMID 28178311, 2017). "To further explore the role of IGF1R signaling pathway in the anti-cancer activity and EMT modulation of phenformin, we examined the specific effects of phenformin on IGF1-induced proliferation, RTK signaling, and the alteration of EMT markers in SKBR3 and 78617 cells." (PMID 28947975, 2017). "By binding and sequestering IGF-1, IGFBP-1 antagonized IGF-1 which could stimulate the proliferation of cancer cells." (PMID 28143425, 2017). "The observed decrease in circulating IGF-1 and IGFBP-3 may contribute to cancer chemopreventive activity." (PMID 28629161, 2017). "Both IGF1 and IGF2 act through the tyrosine kinase insulin-like factor 1 receptor (IGF1R), which is widely overexpressed in multiple childhood sarcomas, including rhabdomyosarcomas, and other cancers such as breast cancer, prostate cancer and lung cancer." (PMID 28793874, 2017). "Insulin is an anabolic hormone able to increase IGF-1 synthesis and activity and IGF-1 in turn may promote cancer development by inhibiting apoptosis, stimulating cell proliferation and sex-steroid synthesis." (PMID 28114909, 2017). "IGF1 and IGF2 are overexpressed in cancer and major therapeutic targets." (PMID 28873464, 2017). "Some TZDs have been shown to reduce levels of the insulin-like growth factor-1 (IGF-1) in the blood, which is a known growth factor that may induce cancer." (PMID 28348577, 2017). "Conversely, insulin-like growth factor binding proteins (IGFBPs) can bind and inactivate IGF-1 to offset its potentially negative effects on cancer outcomes." (PMID 26977321, 2016). "By secretion of soluble factors such as transforming growth factor β (TGF-β), insulin-like growth factor-1 (IGF-1), stroma-derived factor 1 (SDF-1), or fibroblast growth factors (FGFs), CAFs promote tumour angiogenesis and increase invasiveness of cancer cells." (PMID 27852068, 2016). "IGF-1 has a known role in cancer progression, and multiple studies have explored the impact of inhibiting IGF-1 receptor signaling as a potential therapeutic approach for cancers, including neuroblastoma." (PMID 26840089, 2016). "As EMT promotes invasiveness in cancer cells, we then investigated whether the EMT triggered by IGF-1 affected the migration and invasion properties of B16-F10 cells." (PMID 27764776, 2016). "Though the exact links between diabetes and cancer are not known, the exposure to hyperglycemia, elevated insulin, and growth-promoting IGF-1 have been postulated to be the possible reasons explaining the increased incidence of cancers in diabetic patients." (PMID 27512375, 2016). "However, other reports indicate that IGF-1 actually promotes the generation of β amyloid, and therefore additional studies are needed to fully discern the effect of IGF-1 on APP and APLP2 processing and function in cancer." (PMID 26840089, 2016). "IGF-1 is a mitogen, which is usually overexpressed in cancer cells maintaining cell cycle program regulated by the IGF-1R and help in transformation and protection of cancer from apoptosis." (PMID 27806706, 2016). "In older subjects, low protein consumption did not affect significantly IGF1 levels (which physiologically decrease with age) and were correlated with increased rather than decreased cancer mortality." (PMID 26284118, 2015).
cancer (continued). "Furthermore, IR can form hybrid receptors with IGF-1R: IGF-1R/IRB has higher affinity for IGF-1 whereas IGF-1R/IRA has higher affinity for IGF-2 and is involved in cancer signaling pathways." (PMID 25743390, 2015). "AGR2 knockdown does play a significant role in IGF-1-induced cytological behaviors, which indicates that AGR2 function may strongly depend on the cancer microenvironment." (PMID 25956506, 2015). "Tyroscherin showed strong cytotoxicity against IGF-1-dependent cancer cells; however, the vitroprocines were non-toxic to mammalian cells." (PMID 26238555, 2015). "The intensity and duration of Erk phosphorylation in response to IGF-1 in the presence of cell adhesion may be a key determinant of cell phenotype and, in particular, EMT potential of cancer cells." (PMID 26191041, 2015). "Survivin is an apoptosis-inhibitory protein that is over-expressed in multiple cancer types, including HCC, plays critical roles in regulating apoptosis, cell proliferation and survival and has been shown to be a direct downstream target of IGF1 pathway." (PMID 26329608, 2015). "In particular, IGF-1 has been shown to transactivate the promoter sequence of GPER and to upregulate the expression of GPER at both the mRNA and protein levels in ERα-positive breast (MCF-7) and endometrial (Ishikawa) cancer cells." (PMID 25798130, 2015). "Remarkably, our previous findings showed that formononetin, another member of isoflavones family, successfully inactivated insulin-like growth factor 1 (IGF-1)/phosphatidylinositol 3-kinase (PI3K)/protein kinase B (Akt) pathway in MCF-7 cells, leading to inhibition of cancer cell proliferation." (PMID 24618835, 2014). "Moreover, it has been well documented that direct or indirect inhibition of insulin (or IGF-1)/PI3K/Akt/mTOR pathway, such as rapamycin, metformin and dietary protein restriction, have cancer- preventing or treating effects." (PMID 24970814, 2014). "IGF-1-driven cancers showed a pooled RR of 1.21 (95% CI: 1.09-1.36; I2: 67%) versus 1.73 (95% CI: 1.40-2.12; I2: 85%) for those not thought to be driven by IGF." (PMID 25526881, 2014). "Particularly, recent studies favor the notion that attenuation of IGF-1 signaling can protect normal cells, but not cancer cells, against fasting and chemotherapy." (PMID 24970814, 2014). "We have demonstrated in relatively healthy nonagenarians that lower IGF-1 levels significantly predict survival, specifically in females and individuals with a history of cancer." (PMID 24618355, 2014). "Since both IR-A and IR-B are regulated by insulin, IGF1 and IGF2 through autocrine and/or paracrine mechanisms, the microenvironment of the cancer site may also contribute to the relationship of HIR with clinical prognosis and patient survival." (PMID 24571613, 2014). "Both IGF-1 and IGF-2 enhance the proliferation of human cancer cells through IGF-1R and IR-A." (PMID 24171117, 2013). "Despite the small number of cancer cases, there is an epidemiological association of cancer rates in the setting of increased IGF-I levels but not of IGF-binding protein-3 (IGFBP-3), resulting in a high IGF-1 to IGFBP-3 ratio." (PMID 23761782, 2013). "The addition of AS against the IGF-1R mRNA decreased cancer cell growth rate by 70%, both in the presence and absence of exogenous IGF-1 (P < 0.05)." (PMID 24103397, 2013). "Even though the role of PAPPA in cancer has not gathered much attention, IGF-1, the pervasive growth factor whose local bioavailability it regulates, has long been an intense interest for cancer researchers." (PMID 23896451, 2013). "In fact, cancer cell lines, mutant for proteins involved in IGF-1 pathways, failed to respond to CR." (PMID 22934068, 2012). "Cancer patients are reported to have elevated serum levels of growth factors, namely hepatocyte growth factor (HGF), epidermal growth factor (EGF), transforming growth factor-beta (TGF-β) and insulin-like growth factor-1 (IGF-1), among others." (PMID 22432005, 2012).